AQP4 (aquaporin 4)
Diseases named in the same sentence as AQP4 in open-access papers (continued):
Sharing a sentence is not in itself a finding about the gene and the disease.
multiple sclerosis (221 papers, 2012 to 2026). A progressive autoimmune disorder affecting the central nervous system resulting in demyelination. "This cohort included diagnostic serostatus data from anti-Aquaporin 4 antibody testing, providing insights into incidence, demographics, annual relapse rate, and initial misclassification as multiple sclerosis." (PMID 40895228, 2025). "Mislocalization of AQP4 was reported in epilepsy and a loss of AQP4 in astroglial endfeet was found in mouse models of Alzheimer’s disease and multiple sclerosis indicating BBB impairment." (PMID 36882782, 2023). "For many years this disease was considered a variant of multiple sclerosis, but the discovery that most patients have autoantibodies against aquaporin-4 (AQP4) or NMO-IgG changed the understanding of the disease." (PMID 34208272, 2021). "It is associated with an appearance of IgG antibody (AQP4-IgG) targeted to AQP4-expressing astrocytes which distinguishes NMOsd from multiple sclerosis (MS)." (PMID 27941618, 2016). "Smoking and vascular risk factors (VRFs) are reported to have adverse effects in multiple sclerosis but data are limited in aquaporin-4 antibody-positive neuromyelitis optica spectrum disorder (AQP4-NMOSD) and myelin oligodendrocyte glycoprotein antibody disease (MOGAD)." (PMID 40088045, 2025). "Furthermore, rituximab was recommended as first-line DMT for AQP4+ NMOSD in recently updated guidelines from the Swedish Multiple Sclerosis Association." (PMID 38256489, 2024). "However, MOG-AD usually shows more edematous and extensive inflammatory lesions that tend to spare the optic chiasm and tracts when compared to multiple sclerosis-associated or aquaporin-4-positive (AQP4) NMOSD-associated ON." (PMID 38975430, 2024). "Myelin oligodendrocyte glycoprotein antibody-associated disease (MOGAD) is a demyelinating disorder of the central nervous system (CNS) distinct from multiple sclerosis (MS) and aquaporin 4 (AQP4) immunoglobulin G (IgG) antibody-associated neuromyelitis optica spectrum disorder (NMOSD)." (PMID 38783085, 2024). "Higher neutrophil counts and NLR were reported in patients with AQP4+ NMOSD than in healthy controls (HCs) or those with multiple sclerosis (MS)." (PMID 41596603, 2026). "A total of 3 patients presented with > 20 relapses, of which a majority occurred before the availability of AQP4-IgG testing and were treated with interferon-beta because of misdiagnosis of multiple sclerosis." (PMID 41528504, 2026). "This common structure explains the presence of AQP4 depolarization, glymphatic dysfunction, neuroinflammation, and vascular instability in Alzheimer’s disease, Parkinson’s disease, multiple sclerosis, traumatic brain injury, and numerous other disorders." (PMID 41373689, 2025). "Historically misclassified as a variant of multiple sclerosis, NMOSD is now recognized as a distinct nosological entity characterized by specific serological markers, particularly anti-aquaporin-4 (AQP4)-IgG antibodies." (PMID 40933045, 2025). "Initially considered a variant of multiple sclerosis (MS), NMOSD was reclassified as a distinct entity following the identification of autoantibodies targeting aquaporin-4 (AQP4), a water channel protein on astrocytes." (PMID 40701519, 2025). "In clinical validation studies, patients with AQP4-IgG positive NMOSD, multiple sclerosis, or myelin oligodendrocyte glycoprotein antibody-associated disorder and healthy individuals were tested." (PMID 39941228, 2025). "Anti-AQP4 is specifically discerned in NMO patients, and the presence of anti-AQP4 IgG in serum is regarded as the benchmark for distinguishing NMO from multiple sclerosis." (PMID 39441465, 2024). "Multiple sclerosis and aquaporin-4 antibody neuromyelitis optica spectrum disorders are distinct autoimmune CNS disorders with overlapping clinical features but differing pathology." (PMID 39258257, 2024).
multiple sclerosis (continued). "Previously thought to be a variety of multiple sclerosis, the recent discovery of aquaporin-4 (AQP4) water channels allowed for NMO to be distinguished as its own disease process." (PMID 39171010, 2024). "We then examined the relationship between cortical damage, as assessed by cortical T1 relaxation rates and the presence of cortical lesions, and NAWM damage in our multiple sclerosis and AQP4 antibody NMOSD cohorts." (PMID 39258257, 2024). "Pathological features of MOGAD differ from those in multiple sclerosis and AQP4-IgG-positive NMOSD, suggesting that MOGAD is an independent clinical and pathological entity." (PMID 39267735, 2024). "At the study scan, multiple sclerosis patients were younger (M = 35.4, SD = 9.4 years old) when compared with both AQP4 antibody NMOSD patients (M = 50, SD = 13.2) and HC (M = 48.8, SD = 7.9, P < 0.01)." (PMID 39258257, 2024). "In this prospective research MRI study, we have implemented advanced imaging techniques to examine damage in the NAWM in multiple sclerosis and AQP4-IgG-positive NMOSD, as compared to cerebral white matter from HC." (PMID 39258257, 2024). "Multiple sclerosis (MS), aquaporin 4-antibody neuromyelitis optica spectrum disorder (AQP4 + NMOSD) and myelin oligodendrocyte glycoprotein antibody–associated disease (MOGAD) are the most defined forms." (PMID 38646958, 2024). "Because NMO mimics multiple sclerosis, diagnosing it is difficult and necessitates particular testing, such as magnetic resonance imaging (MRI) and aquaporin-4 antibody detection." (PMID 39022489, 2024). "ITM is thought to represent a distinct feature even in the “post-aquaporin-4 (AQP4) antibody era”, especially in East Asia, where the incidence of multiple sclerosis and neurosarcoidosis is very low." (PMID 37749508, 2023). "Its clinical features and immunopathological mechanisms are distinct from both classic multiple sclerosis (MS) and aquaporin-4 (AQP4)-IgG-positive NMOSD, and being considered as a disease entity in its own, i.e. MOG antibody-associated disease (MOGAD)." (PMID 37342342, 2023). "The distinctive characteristic of this disease is the presence of antibodies against the aquaporin-4 water channel (AQP4), permitting the clinician to differentiate it from a severe form of multiple sclerosis." (PMID 36983602, 2023). "NMOSD is distinct from multiple sclerosis due to the presence of autoantibodies against the astrocytic water channel protein aquaporin-4 (AQP4-IgG)." (PMID 37754247, 2023). "Several neurological diseases, such as Alzheimer's disease, Parkinson's disease, multiple sclerosis, and traumatic brain injury (TBI) are associated with glymphatic dysfunction attributed to perturbation of AQP4 expression or disruption of AQP4 polarization." (PMID 37353947, 2023). "Glymphatic dysfunction has been demonstrated in rodent models, such as not limited to TBI, AD, and multiple sclerosis (MS), and is probably related to the disturbance of aquaporin-4 (AQP4) expression." (PMID 37024941, 2023). "The discovery of aquaporin-4 antibodies (AQP4-abs) in 2004 has enhanced our understanding of NMOSD as it was a critical distinction from multiple sclerosis (MS)." (PMID 38021935, 2023). "Changes in AQP4 expression and/or distribution have been found in neurological disorders such as amyotrophic lateral sclerosis, multiple sclerosis, and epilepsy, as well as in Alzheimer’s disease and in TBI24." (PMID 33479350, 2021). "In contrast to that reported in multiple sclerosis, results of this cohort study suggest that new remission silent lesions are rare on follow-up scans in MOGAD and AQP4-NMOSD and appear to indicate a high risk of imminent relapse." (PMID 34878547, 2021). "Overall, the levels of a select few metabolites discriminate between NMOSD and multiple sclerosis and between AQP4-Ab+ NMOSD and MOG-Ab+." (PMID 32961928, 2020).
multiple sclerosis (continued). "AQP4-antibody disease has a high female-to-male ratio (up to 9:1), and its mean age at onset of ~40 years is later than that seen in multiple sclerosis." (PMID 32670177, 2020). "This mini-review/commentary is primarily intended to discuss these results in the context of two neuroinflammatory conditions affecting the spinal cord: multiple sclerosis and the anti-AQP4 autoantibody-mediated disorder neuromyelitis optica (NMO)." (PMID 32033173, 2020). "The discovery of an association of NMO with the presence of serum antibodies against aquaporin 4 (AQP4) facilitated the diagnostic process of the disease and allowed for better differentiation between NMO and multiple sclerosis (MS) variants." (PMID 33022898, 2020). "The proof of serum autoantibodies directed against aquaporin-4 (AQP4-IgG) in around 80% of cases established NMOSD as a distinct disease from multiple sclerosis (MS)." (PMID 33101166, 2020). "First, we analysed a panel of 32cytokines/chemokines in a discovery group (nine aquaporin-4-antibodyseropositive, nine myelin oligodendrocyte glycoprotein-antibodyseropositive, eight encephalitis, 10 multiple sclerosis)." (PMID 31205739, 2019). "MOG antibody disease spontaneously separated from multiple sclerosis, but overlapped with AQP4 antibody disease." (PMID 31212763, 2019). "Astrocytic impairment associated with the loss of AQP4 is a pathologic feature of NMOSD, which is distinct from multiple sclerosis (MS)." (PMID 30426010, 2018). "In contrast to multiple sclerosis, autoantibodies against aquaporin-4 (AQP4) expressed on astrocytic end-feet have been exclusively detected in sera of NMOSD patients." (PMID 30083159, 2018). "In conclusion, this is the first study done in Sri Lanka to meticulously characterize multiple sclerosis both clinically and paraclinically taking into consideration both OCBs and AQP4 antibody status." (PMID 29682349, 2018). "MOG-IgG-related encephalomyelitis (MOG-EM) is now considered by many experts a disease entity in its own right, pathogenetically distinct from both classic multiple sclerosis (MS) and aquaporin-4 (AQP4)-IgG-positive neuromyelitis optic spectrum disorders." (PMID 29554927, 2018). "The presence of aquaporin-4 (AQP4) antibody in NMO facilitates its distinction from multiple sclerosis, and many studies have shown that AQP4 autoimmune lesions outside the optic nerve and spinal cord are common." (PMID 28293214, 2017). "Myelin oligodendrocyte glycoprotein antibody (MOG Ab) associated demyelination represents a subgroup of autoimmune demyelination that is separate from multiple sclerosis and aquaporin 4 IgG-positive NMO, and can have a relapsing course." (PMID 26919719, 2016). "In contrast to multiple sclerosis (MS), NMO is associated with autoantibodies that target the aquaporin-4 water channel on astrocytes (anti-AQP-4 antibody)." (PMID 24886528, 2014). "Although these autoantibodies present an invaluable biomarker for NMOsd and for the differential diagnosis of multiple sclerosis (MS), diagnosis of anti-AQP4-seronegative NMOsd remains challenging." (PMID 24086369, 2013). "Myelin oligodendrocyte glycoprotein antibody associated disease (MOGAD) defines a subgroup of patients with central nervous system (CNS) inflammation with MOG-IgG that is distinct from multiple sclerosis (MS) and aquaporin-4 (AQP4)-IgG positive neuromyelitis optic spectrum disorder (NMOSD)." (PMID 39148657, 2024). "Moreover, NMOSD can be distinguished from multiple sclerosis (MS) by discovering anti aquaporin-4 antibody (AQP4)." (PMID 38463921, 2024). "Fatigue is frequently reported by patients with multiple sclerosis, aquaporin-4-antibody neuromyelitis optica spectrum disorder and myelin-oligodendrocyte-glycoprotein antibody disease; thus they could share a similar pathophysiological mechanism." (PMID 37180990, 2023).
multiple sclerosis (continued). "Therefore, AQP4-IgG is considered a pathogenic marker of NMOSD, and the presence of AQP4-IgG unequivocally distinguishes NMOSD from multiple sclerosis (MS)." (PMID 35585974, 2022). "These hyalinized vessel walls with deposits of immunoglobulins and complement activation products in the characteristic vasculocentric rim and rosette pattern, and AQP4 loss, are not observed in the lesions of multiple sclerosis patients." (PMID 34445343, 2021). "When specific pathogenic aquaporin-4 (AQP4) autoantibodies were detected in a major subset of patients at the beginning of the 21st century, NMOSD were finally considered to belong to a disease entity distinct from multiple sclerosis." (PMID 33419217, 2021). "Because the expected visual prognosis is generally worse in AQP4‐IgG‐positive NMOSD than in other multiple sclerosis and related disorders, active acute treatments with or without adjunctive plasma exchange are required in patients with ON related to AQP4‐IgG." (PMID 33591639, 2021). "Five patients experienced radiologically demonstrated transverse myelitis, one of whom had positive serum aquaporin-4 antibodies detected at Mayo Clinic, and five patients showed radiologic evidence of demyelination consistent with multiple sclerosis." (PMID 32644976, 2020). "No novel or missense variants in the AQP4 gene were found in Mexican patients with NMO or multiple sclerosis." (PMID 32792643, 2020). "The diffuse increased expression of AQP4 was verified in chronic-active multiple sclerosis lesions." (PMID 32998402, 2020). "Thus, we concluded that mesenchymal stem cells alleviated blood-brain barrier disruption by downregulating AQP4 in multiple sclerosis, possibly through inhibiting the A2BAR/p38 MAPK signaling pathway." (PMID 32613467, 2020). "The presence of AQP4-IgG unequivocally differentiates NMOSD from multiple sclerosis." (PMID 32961928, 2020). "Other studies demonstrated that MRI brain lesion distribution criteria may help to distinguish MOG-IgG+ and AQP4-IgG+ patients from multiple sclerosis patients." (PMID 33101166, 2020). "The concept of epitope spreading has been reported in multiple sclerosis, AQP4 Ab in NMO, but not in MuSK Ab-associated myasthenia gravis, nor in 11 paediatric MOG Ab responses." (PMID 31481127, 2019). "Therefore, the main objective of our study is to assess positivity for AQP4‐Ab in patients presenting with inflammatory demyelinating central nervous system (CNS) diseases other than typical multiple sclerosis (MS) in Lithuania." (PMID 30284401, 2018). "Myo-inositol was previously reported to be low within spinal cord lesions in a group of 5 NMOSD patients (2 AQP4-Ab positive and 3 negative) and elevated white matter myo-insoitol has been linked with multiple sclerosis." (PMID 29208041, 2017). "The discovery of the NMO-immunoglobulin G (NMO-IgG) antibody in the serum of patients with this condition and subsequent identification of the target antigen anti-aquaporin-4 (AQP4) suggested that the pathogenesis of NMO differs from that of multiple sclerosis (MS)." (PMID 27171423, 2016). "All must be presentAcute myelitisOptic neuritisAt least two of the three supportive criteria are: o Contiguous spinal cord MRI lesion extending over 3 vertebral segments o Brain MRI does not meet the diagnostic criteria for multiple sclerosis. o Aquaporin-4 IgG seropositive status." (PMID 37841344, 2023). "Conversely, AQP4 might be upregulated in astrocytes as a compensatory event in multiple sclerosis." (PMID 35536323, 2022). "Using recombinant monoclonal IgG1, the loss of OPCs is practically complete in NMOSD, unlike in multiple sclerosis, in which it decreases to 50%; therefore, with the presence of AQP4–IgG, remyelination may be difficult." (PMID 34068922, 2021).
multiple sclerosis (continued). "However, NMO was traditionally considered as a variant of Multiple Sclerosis (MS), but after the discovery of a disease-specific immunoglobulin G antibody (NMO-IgG) that selectively binds to aquaporin-4 (AQP4; the most abundant water channel in the CNS), it is now considered as a distinct disease." (PMID 32214385, 2020). "Fatigue is a common and disabling symptom amongst people with multiple sclerosis, however it has not been compared across the central nervous system (CNS) inflammatory diseases associated with aquaporin‐4 (AQP4) and myelin oligodendrocyte glycoprotein (MOG) antibodies (Ab)." (PMID 32187851, 2020). "Detection of AQP4-specific autoantibodies (AQP4-IgG, also known as NMO-IgG) in patients’ serum is crucial for diagnosing NMO and distinguishes it from multiple sclerosis (MS)." (PMID 41480772, 2026). "AQP4-IgG is highly useful for differentiating NMOSD from other inflammatory diseases of the CNS, such as multiple sclerosis (MS) and myelin oligodendrocyte glycoprotein antibody-associated disease (MOGAD)." (PMID 39941228, 2025). "Aquaporin-4 antibodies have been identified as a distinguishing biomarker of NMOSD, allowing for differentiation from multiple sclerosis and other mimicking neurological conditions." (PMID 40901465, 2025). "Traditionally mistaken for multiple sclerosis due to overlapping symptoms, NMOSD has now been recognized as a distinct disease, particularly following the discovery of antibodies against aquaporin-4 (AQP4-IgG)." (PMID 40410835, 2025). "In terms of CNS demyelinating diseases, we recently reported that CSF neopterin levels are elevated in patients with AQP4-IgG-positive NMOSD and MOGAD compared to those in patients with multiple sclerosis." (PMID 39124808, 2024). "AQP4 antibodies (AQP4-abs) have been identified as key differentiators between NMOSD and other CNS demyelinating conditions, such as multiple sclerosis." (PMID 38737586, 2024). "A specific antibody to astrocyte (AS), aquaporin-4 (AQP4), is detected in 60–80% of patients with NMOSD, which is a major differentiating feature that differentiates NMOSD from multiple sclerosis (MS)." (PMID 35729649, 2022). "In recent years, NMO, which is a more specific aquaporin 4 (AQP4) antibody, separates NMO from multiple sclerosis (MS)." (PMID 35360267, 2022). "TDL can emerge not only as part of the spectrum of classic multiple sclerosis (MS) but also can represent an idiopathic monophasic disease, a relapsing disease with recurrent TDL, or could be part of the myelin oligodendrocyte glycoprotein (MOG)- and aquaporin-4 (AQP4)-associated disease." (PMID 35418930, 2022). "AQP4-antibody (AQP4-ab) presence is highly specific, and differentiates NMO from multiple sclerosis." (PMID 34530847, 2021). "Finally, the genetic susceptibility of the NMO group negative for AQP4-Ab needs to be analyzed with caution because optic spinal disease could be related to Asian type MS, Conventional Multiple Sclerosis, or MOG-IgG related disorders." (PMID 33420337, 2021). "Plasma lipoproteins, along with perturbations of amino acids, scyllo-inositol, and myo-inositol, have been shown to discriminate between AQP4-Ab+ NMOSD, AQP4-Ab− NMOSD, and multiple sclerosis." (PMID 32961928, 2020). "Since the discovery of NMO-IgG, an NMO-specific autoantibody directed against aquaporin-4 (AQP-4), neurologists have identified NMOSD as a distinct neuropathy from multiple sclerosis." (PMID 31852443, 2019). "The discovery of a highly specific autoantibody against the aquaporin-4 (AQP4) water channel (AQP4-IgG) unified a spectrum of NMO-related disorders and distinguished them from multiple sclerosis (MS)." (PMID 27371173, 2016). "Detection of IgG anti-Aquaporin-4 (AQP4) in serum of patients with Neuromyelitis optica syndrome disorders (NMOSD) has improved diagnosis of these processes and differentiation from Multiple sclerosis (MS)." (PMID 27455255, 2016).